ACHE (acetylcholinesterase (Yt blood group))
Diseases named in the same sentence as ACHE in open-access papers (continued):
Sharing a sentence is not in itself a finding about the gene and the disease.
Stroke (17 papers, 2008 to 2025). Sudden impairment of blood flow to a part of the brain due to occlusion or rupture of an artery to the brain. "A recent meta-analysis-based study highlights that galantamine and other AChE inhibitor treatments are associated with lower risk of CV events including stroke, acute coronary syndrome, and cardiovascular mortality." (PMID 33776997, 2021). "A severe decrease in AChE activity after stroke has been associated with a poor prognosis." (PMID 37873057, 2023). "However, AChE is known to induce apoptosis and form apoptosomes, and low AChE level was a significant risk factor reflecting the activation post-stroke cholinergic anti-neuroinflammatory process in a study against stroke patients." (PMID 34072449, 2021). "In the present study we report increased levels of neuronal levels of AChE in male stroke patients and increased levels of ChAT in both stroke females and males." (PMID 40950018, 2025). "The introduction of an oxime group into an appropriate chemical backbone has produced very effective AChE reactivators, various kinase inhibitors, and compounds with antibacterial, anticancer, anti-inflammatory, anti-arthritis, and anti-stroke activities." (PMID 38203326, 2023). "It has further been demonstrated that, the activity of acetylcholine esterase (AChE) dimers decreases with age, which provides additional evidence that aging patients are more likely to suffer post-stroke dementia." (PMID 37199575, 2023). "First, due to the complex process and pathways of post-stroke neuroinflammation, we assume that there are more complicated interactions and molecules involved between the AChE and microglial activation, than we suggested." (PMID 34072449, 2021). "Previous studies that have investigated the effect of AChE inhibitor after stroke only focused on the improvement of cognitive functions." (PMID 34072449, 2021). "In conclusion, our study shows that the post-stroke neuroinflammatory process can be demonstrated with AChE and TSPO PET imaging, and suggests the future possibility of its utilization as a prognostic and therapeutic biomarker." (PMID 34072449, 2021). "Acetylcholinesterase (AChE) has recently come into focus as a post-stroke neuroinflammatory factor, which is one of the major components of the cholinergic system." (PMID 34072449, 2021). "Spearman’s correlation revealed that plasma AChE activity was negatively correlated with age in both healthy controls (r = −0.343, p = 0.0002) and stroke patients (r = −0.368, p < 0.0001)." (PMID 31653081, 2019). "Clinical study also showed that serum AChE activity was inversely and prominently correlated with inflammatory markers in post-stroke patients." (PMID 26107885, 2015). "Additionally, by administrating donepezil, we demonstrated that the microglial activity was reduced by the inhibition of AChE activity during the early phase of stroke." (PMID 34072449, 2021). "AChE and BChE are two major enzymes regulating the plasma level of Ach, which binds a muscarinic receptor on macrophages to regulate the inflammatory response after stroke." (PMID 31653081, 2019). "Taken together, these results suggest that AChE dysfunction is a result of stroke rather than a cause for further neurodegeneration." (PMID 31653081, 2019). "In addition, in stroke patients, reduced AChE activity was correlated with lower survival rate." (PMID 31653081, 2019). "In humans, accumulating evidence indicates that AChE is directly or indirectly involved in the regulation of inflammatory responses or functions as a predictor of inflammation, usually correlated with multiple inflammatory markers, such as those in patients with inflammatory bowel disease or stroke." (PMID 28178923, 2017). "Therefore, downregulation of AChE and upregulation of ChAT may compensate for reduced ACh levels in brains with AD disease or stroke and may facilitate ischemia-induced memory functional recovery." (PMID 24194776, 2013).
Stroke (continued). "The number of anti-stroke plants is not always consistent with the number of candidate anti-stroke compounds, such as target AChE and FII." (PMID 28117389, 2017). "We noted that some non-anti-stroke plants in Groups 2 and 3 have more compounds can interact on target AChE." (PMID 28117389, 2017).
type 2 diabetes (17 papers, 2013 to 2025). "On the other hand, increased AChE has been reported in many low-grade inflammatory diseases like Alzheimer’s and type 2 diabetes." (PMID 37027384, 2023). "These key enzymes can control the occurrence of type II diabetes (α-amylase and α-glucosidase), obesity (lipase) and AD (acetylcholinesterase (AChE), butyrylcholinesterase (BChE) and β-secretase (BACE-1))." (PMID 35684288, 2022). "AChE activity in the hippocampus was significantly increased in the type 2 diabetes model group versus healthy controls (p < 0.01)." (PMID 34834352, 2021). "Depending on the level of AChE inhibition, cholinergic motivation may lead to hyperactivity of excitable tissues, causing fasciculations, seizures, convulsions, severe muscle paralysis, hypersecretion from secretory glands, respiratory failure, coma, and death." (PMID 24453891, 2013). "In addition, it is reported that plasma and tissue concentrations of butyrylcholinesterase and AChE were elevated in type 2 diabetes and AD26." (PMID 32238886, 2020). "Similarly, the calyx and fruit extracts showed greater effectiveness in inhibiting the AChE, BChE, α-glucosidase, and α-amylase enzymes, indicating possible applications in the treatment of neurodegenerative diseases and metabolic disorders such as type 2 diabetes." (PMID 40227212, 2025). "Recent research has also shown that hyperglycemia in type 2 diabetes significantly affects both STM and LTM, accompanied by altered AChE activity and significant inflammatory responses in the hippocampus and prefrontal cortex." (PMID 40726602, 2025).
Hyperglycemia (15 papers, 2011 to 2025). An increased concentration of glucose in the blood. "In the study, an increased hippocampal AChE expression was spotted in obese rats linked with hippocampal inflammation instigated by hyperglycemia and oxidative stress." (PMID 36304965, 2022). "Using paraoxon as a systemic AChE inhibitor, we demonstrate that cholinergic activation prevents the development of hyperglycemia by inhibiting pancreatic islet inflammation and β cell loss." (PMID 27790217, 2016). "Acetylcholinesterase (AChE) inhibition has been proposed to underlie OP-induced hyperglycemia." (PMID 22073164, 2011). "Treatment with galantamine reduced both apoptotic markers, possibly through reducing fatty acids and/or inhibiting AChE, where ample of evidence point to the involvement of AChE in apoptosis, especially that induced by selective stressors as hyperglycemia." (PMID 26262991, 2015). "However, hyperglycemia for 45 days significantly decreased AChE activity in the prefrontal cortex (P = 0.012) compared to the sham group." (PMID 40726602, 2025). "Increased FFA and hyperglycemia-induced oxidative stress were related to changes in AChE activity." (PMID 36304965, 2022). "Consistent with this conclusion, inhibition of AChE failed to prevent STZ-induced hyperglycemia in IFNγ-deficient mice." (PMID 27790217, 2016). "Hence, inhibition of AChE activity plays a role to some extent in CPF-induced hyperglycemia." (PMID 35457505, 2022). "The present study suggests that A. asphodeloides and its active extracts and components are worth further investigation and might be expected to develop as a candidate for the treatment or prevention of oxidative stress-related diseases, AChE inhibition, and hyperglycemia." (PMID 35204266, 2022). "Interestingly, inhibition of AChE fails to modulate streptozotozin (STZ)-induced hyperglycemia in IFNγ-deficient (IFNγ−/−) mice, demonstrating the crucial role played by IFNγ in ACh-mediated inhibition of the autoimmune response against islet β cells." (PMID 27790217, 2016). "To date, there is no FDA approved drug that can manage both hyperglycemia and AD via targeting of α-amylase and AChE." (PMID 36986895, 2023). "The level of AChE in hyperglycemia-induced rats was significantly higher than in the negative control group." (PMID 35802659, 2022). "AChE inhibition is the prime mode of action of OP but in our study both humans and mice exposed to chronic OPs developed hyperglycemia but no changes in the level of plasma AChE activity is observed." (PMID 28115022, 2017). "Moreover, we have preliminary evidence that other AChE inhibitors, such as galantamine and rivastigmine, also prevent the development of hyperglycemia in the MLD-STZ model (data not shown)." (PMID 27790217, 2016).
Sepsis (15 papers, 2017 to 2024). Sepsis is defined as life-threatening organ dysfunction caused by a dysregulated host response to infection. "This study aimed to investigate the involvement of AChE activity in sepsis and evaluate its association with disease severity and clinical outcomes." (PMID 37626609, 2023). "Increasing the sample size in future studies would enhance the sensitivity of our findings and improve the ability to detect significant associations between AChE activity and sepsis outcomes." (PMID 37626609, 2023). "The sustained increase in AChE activity warrants further investigation to better understand its underlying mechanisms and potential implications in the pathophysiology of sepsis." (PMID 37626609, 2023). "The findings of our study show that CLP-induced sepsis caused a significant and time-dependent decline in AChE activity." (PMID 30804708, 2019). "For example, a SNP in the miR-608-binding motif of the AChE gene associates with several MetS hallmarks, whereas another SNP in the miR-608 gene itself limits the risk of sepsis in head injury patients." (PMID 29922126, 2018). "In addition, IL-1β induced AChE mRNA expression in vivo and activity in vitro, reflecting the pro-inflammatory scenario caused by sepsis." (PMID 37153798, 2023). "These drugs can impact AChE activity directly or indirectly, leading to changes that might mask or influence the association between AChE activity and sepsis outcomes." (PMID 37626609, 2023). "The delayed decrease in AChE activity in the treated animals compared to that in the control group could be associated with the positively influenced course of sepsis in the treated animals." (PMID 30804708, 2019). "Specifically, we focused on patients with sepsis and examined both short-term and long-term effects of AChE activity on disease severity." (PMID 37626609, 2023). "Further investigations are required to elucidate the complex dynamics of AChE activity and its implications in sepsis." (PMID 37626609, 2023). "Future research with larger cohorts and more precise timing of sepsis onset is warranted to further investigate the role of AChE activity in sepsis pathophysiology." (PMID 37626609, 2023). "One possible explanation for our unexpected findings is the timing of sepsis detection and the initial measurement of AChE activity." (PMID 37626609, 2023). "The AChE activity in this brain structure was significantly lower than in WT mice 13 days after sepsis induction (p < 0.0001)." (PMID 37153798, 2023). "AChE activity at the end of the observation period surpassed preoperative baseline values, consistent with the literature, contradicting a sepsis impact." (PMID 37629287, 2023). "Investigating the synergistic effect of combining AChE activity with other relevant biomarkers in sepsis research holds promise for enhancing our understanding of the disease pathophysiology." (PMID 37626609, 2023). "One interesting finding of our study is that AChE activity remained unaltered during the first 7 days following sepsis detection." (PMID 37626609, 2023). "This study serves as an exploratory investigation, aiming to provide preliminary insights into the relationship between AChE activity and sepsis." (PMID 37626609, 2023). "Considering the relation between sepsis and the cholinergic pathway, we evaluated AChE activity in the brain of sepsis-surviving mice." (PMID 37153798, 2023). "The levels of ChAT were increased in sepsis groups compared with those in sham groups, while AchE exhibited lower expression in the brain tissues of septic mice than those of sham mice." (PMID 34512319, 2021). "In patients with sepsis and suspected SAE, inflammation appears to be a major cause for the alteration of cholinergic metabolism and thus AChE-activity." (PMID 33203376, 2020). "Our study was aimed at exploring the effects of NRG-1β application on diaphragmatic contractility and AChE activity during sepsis." (PMID 32765805, 2020).
Sepsis (continued). "Our previous study verified that AChE activity decreased at the NMJ in the diaphragm during sepsis and oxidative stress was a vital contributor." (PMID 32765805, 2020). "Compared with the sham group, AChE activity decreased significantly in both the sepsis and the NRG groups 24 h after surgery (P < 0.01)." (PMID 32765805, 2020). "NRG-1β inhibited proinflammatory cytokine release and muscle injury biomarkers soaring in serum and improved the sepsis-induced diaphragm dysfunction and AChE activity decrease significantly during sepsis." (PMID 32765805, 2020). "The decrease in AChE activity correlated with the development of a lactate acidosis, a conventional indicator of poor outcomes in sepsis." (PMID 30804708, 2019). "Decreased AChE activity can be associated with elevated proinflammatory markers (ROS production, CD11b expression) in the circulation during CLP-induced sepsis." (PMID 30804708, 2019). "Our recent study demonstrated that acetylcholinesterase (AChE) activity at the neuromuscular junction (NMJ) of the diaphragm decreased during sepsis." (PMID 29230271, 2017). "In the current study, we detected AChE activity in two different grades of sepsis to more intensively determine the effects of sepsis on AChE activity." (PMID 29230271, 2017). "First, we found that AChE activity at the NMJ of diaphragm decreased more significantly during severe sepsis for the first time." (PMID 29230271, 2017). "AChE activity in the hippocampus was significantly increased among sepsis survivors (n = 8 per group)." (PMID 29326685, 2017). "In the hippocampus and the cortex of mouse sepsis survivors, the activity of acetylcholinesterase (AChE), the enzyme that degrades acetylcholine, as well as the expression of its encoding gene were significantly increased." (PMID 29326685, 2017). "We aimed to clarify the role of oxidative stress in the decreased AChE activity at the NMJ of diaphragm during sepsis." (PMID 29230271, 2017). "In sepsis survivors, we observed a trend toward higher AChE activity and significantly increased Ache gene expression in the cortex." (PMID 29326685, 2017). "Meanwhile, we measured the indicators of oxidative injury (thiobarbituric acid reactive species (TBARS) and protein carbonyl) to observe the correlation between AChE activity and oxidative stress during sepsis." (PMID 29230271, 2017). "The plasma activity of AChE and BuChE may be altered due to a variety of stimuli including inflammation, major trauma, burns and sepsis." (PMID 38321383, 2024). "We hypothesize that AChE activity may be altered during sepsis, similar to sterile traumatic injury, and could potentially serve as an early indicator of disease progression." (PMID 37626609, 2023). "However, we observed a mild but significant reduction in AChE activity 28 days following sepsis detection." (PMID 37626609, 2023). "Sterile inflammation and pathogen-induced sepsis might trigger different regulatory pathways, leading to divergent effects on AChE activity." (PMID 37626609, 2023). "AChE activity was measured at sepsis detection, as well as 7 and 28 days later." (PMID 37626609, 2023). "Given roles of ChAT and AchE in the synthesis and degradation of Ach respectively, the different performance of ChAT and AchE in response to sepsis suggested the enhanced activation of cholinergic system by increasing the production but decreasing the degradation of Ach." (PMID 34512319, 2021). "Our research is in line with work in which oxidative stress might be responsible for a decreased AChE activity in the diaphragms of rats induced with sepsis." (PMID 34306747, 2021). "However, the effects of NRG-1β on diaphragmatic contractility and AChE activity during sepsis have yet been explored." (PMID 32765805, 2020). "First, our study found that NRG-1β could prevent diaphragmatic function and AChE activity during sepsis for the first time." (PMID 32765805, 2020).